IL6 (interleukin 6)
Diseases named in the same sentence as IL6 in open-access papers (continued):
Sharing a sentence is not in itself a finding about the gene and the disease.
osteoporosis (continued). "IL-6 and TNF-α are also pro-osteoclastic molecules that are markedly increased in patients with osteoporosis." (PMID 36615792, 2022). "Bone resorption is predominantly induced by IL-6, IL-1β and TNF-α in osteoporosis, especially in the post-menopausal patients." (PMID 35381577, 2022). "MLN64-knockdown alleviates the severity of osteoporosis, down-regulates specific genes related to osteoclastogenesis including Runx2 and inflammatory factors such as TNF-α, IL-1β, IL-6, and MMP-1." (PMID 36387862, 2022). "It is important to note that the remodelling process involves the role of interleukin-6 in DOMS, anterior cruciate ligament injury, OA and osteoporosis as well." (PMID 36012312, 2022). "Subgroup analysis for T2D patients revealed an increase in TGF-β, IL-6 and SCTX in the osteoporosis group, while a decreased PINP in the osteoporosis group compared to the other two subgroups." (PMID 36578954, 2022). "Finally, at logistic regression model, baseline DAS44 [OR: 2.46 (1.11–5.44)] and osteopenic/osteoporosis status [OR: 7.13 (1.27–39.94)] arose as independent factors of erosiveness, whereas baseline IL-6 plasma levels were not independently associated with bone erosions presence in ERA." (PMID 33732715, 2021). "As IL-6 and TNF contribute to osteoclastogenesis, blockade of IL-6 and TNF can protect against osteoporosis in RA patients." (PMID 34681582, 2021). "After 3 months of ST treatment, the IL-6 and TNF-α levels of the rats in the OVX+ST group were reduced, and the TGF-β1 content was higher than model rats, indicating that ST can improve osteoporosis, which the effect is slightly lower than ALE." (PMID 32670052, 2020). "Serum IL-6 levels in patients with s-JIA correlate with the extent and severity of joint involvement, fever patterns, growth retardation, and osteoporosis." (PMID 31924225, 2020). "Both IL-6 and TNF-α promote bone resorption, and the positive correlation of DANCR with serum levels of IL-6 and TNF-α in osteoporosis patients suggest the involvement of DANCR in the pathology of osteoporosis." (PMID 32992908, 2020). "In this study, we tried to evaluate the relationships among 14-3-3η protein, TNF-α, and IL-6, I-CTX and PINP, and analyzed the mechanism of 14-3-3η protein affecting the development of osteoporosis in patients with RA." (PMID 32704255, 2020). "In vitro and in vivo studies have shown that the proinflammatory cytokines IL-6 and TNF-α are involved in the pathogenesis of osteoporosis and influence bone metabolism." (PMID 32963568, 2020). "Research also showed that resistin, leptin, IL-1, IL-4, IL-6, and TGF-β played a significant role in postmenopausal women’s bone metabolism and could be used as a diagnostic marker capable of recognizing patients at risk of osteoporosis and thereby predicting the risk of fracture." (PMID 33519717, 2020). "Increased expression of related indicators in this study suggested the effect of inflammatory factors such as IL-18, IL-6 and hs-CRP on osteoporosis." (PMID 31258577, 2019). "There was a non-significant tendency to have a greater number of exacerbations, IL-6 levels and lower FFMI and muscle strength in subjects with osteoporosis." (PMID 31601899, 2019). "Generally, a Th1 profile and the hyperproduction of pro-inflammatory cytokines, mainly IL-1, IL-6, IL-17 and tumor necrosis factor (TNF)-α, condition the appearance and progression of both primitive and secondary osteoporosis." (PMID 30846811, 2019). "In fact, several in vitro and rodent studies have revealed that proinflammatory cytokines such as interleukin-6 (IL-6), interleukin-1 (IL-1), and tumor necrosis factor-alpha (TNF-α) are involved in the pathogenesis of osteoporosis." (PMID 29996796, 2018). "Serum IL-1β, IL-6, NTx, and PTH levels in women with osteoporosis were significantly higher than controls." (PMID 28121926, 2017).
osteoporosis (continued). "Thus, our data as well as results of other investigators allow us to hypothesize that the crosstalk between IL-6 and Wnt signaling pathways represents a novel key mechanism for regulation of the homeostasis of joint tissues involved in pathogenesis of RA and osteoporosis progression." (PMID 27106351, 2016). "IL-17 induces osteoblast and stromal cell production of IL-6, and TNF, which induce RANKL expression, accelerate osteoclastogenesis and lead to osteoporosis." (PMID 24400116, 2014). "In this study, the downregulation of IL-6, TNF-α, IL-1β, MMP3, MMP9, and caspase-3 by curculigoside aligns with previous findings that these factors mediate osteoblast injury and extracellular matrix degradation in osteoporosis." (PMID 40917365, 2025). "Since Periostin is secreted by osteoblasts, and these have a substantial impact on bone homeostasis and osteoporosis, we investigated the expression of Periostin in human osteoblasts and its effects on osteogenic differentiation as well as OPG and IL-6 secretion." (PMID 39940700, 2025). "In PWH, the presence of IL-6 and also the UPAR has been linked to non-AIDS malignancies as well as chronic kidney disease or osteoporosis." (PMID 40924496, 2025). "Interestingly, in the Framingham Osteoporosis Study, a relationship between CRP (an acute phase inflammatory marker downstream of IL-6) and higher femoral neck aBMD was observed in postmenopausal women using menopausal hormone therapy." (PMID 40329072, 2025). "Additionally, PPARG, PTGS2, IL6, STAT3, and JUN have been reported to play important roles in the development of osteoporosis." (PMID 40299567, 2025). "Osteoporosis was more common in RA cases compared to non-RA cases (19.1% vs. 0%; p = 0.007) and cellular expression levels of IL-6 were higher in RA cases vs. non-RA cases (48.7% vs. 34.7%; p = 0.000)." (PMID 39766906, 2024). "The accumulation of local inflammatory factors such as IL-1, IL-6, RANKL, and IL-17 may facilitate osteoclast activation, exacerbate osteoporosis progression and contribute to severe localized pain in patients." (PMID 38994021, 2024). "Hence, the immune microenvironment, comprising immune cells and inflammatory factors (IL-1β, IL-18, IL-17, IL-6, and TNF-α), plays a pivotal regulatory role in bone metabolism and contributes to the pathogenesis of osteoporosis." (PMID 38895114, 2024). "In addition, IL-6 and TNF-α can enhance the bone resorption capacity of PBMCs, stimulate the formation of osteoclasts and contribute to the development of osteoporosis." (PMID 37525169, 2023). "In this osteoporosis rat model study, RSV supplementation protected against MTX-induced bone damage by inhibiting osteoclastogenesis (reducing TRAP levels) and lowering proinflammatory cytokines such as TNF, IL1, and IL6." (PMID 37239124, 2023). "A number of inflammatory cytokines, most notably interleukin-6 (IL)-6, interleukin-1β (IL-1β), and tumor necrosis factor-α (TNF-α), were identified as major players in the pathogenesis of RA as well as RA-related comorbidities, such as osteoporosis." (PMID 36431340, 2022). "A previous study showed that significant upregulation of IL-6 levels was observed in osteoporotic BMMCs compared with normal controls, suggesting IL-6 as a promising target for osteoporosis therapy." (PMID 34986839, 2022). "In bone tissue, IL-6 stimulates RANKL, which is indispensable for osteoclast differentiation and activation, and its effect would be in conjunction with that of IL-1β, leading to bone resorption and osteoporosis." (PMID 36184700, 2022). "As DANCR correlated to IL6 and TNFα in patients affected by osteoporosis it was suggested that the long and non-coding RNA-DANCR could be used as a biomarker in osteoporosis." (PMID 34640633, 2021). "Serum immunomodulatory factors IL-6 and TNF-α can aggravate osteoporosis." (PMID 32670052, 2020).
osteoporosis (continued). "In addition, inflammation is closely related to osteoporosis, in which IL-1β, TNF-α, and IL-6 can activate the macrophages of the NF-κB pathway, thereby causing them to differentiate into osteoclasts." (PMID 31470845, 2019). "Furthermore, IL-6 and TNF-α levels were also correlated with DANCR expression in low-BMD osteoporosis patients." (PMID 30937214, 2019). "Among the pathological factors contributing to the frequent incidence of osteoporosis, increased secretion of pro-inflammatory cytokines such as interleukin (IL)-1, IL-6, IL-17, and tumor necrosis factor-alpha (TNF-α) suggests an intimate relationship between inflammation and osteoporosis 1-3." (PMID 31595160, 2019). "Currently, targeting IL-6 therapeutically for osteoporosis has not been explored, but this is an interesting clinical future direction that holds great potential if the side effects from these types of therapies can be minimized." (PMID 30671025, 2018). "Besides, naringin improved random skin flap survival and osteoporosis through promoting angiogenesis by regulating the VEGF/VEGFR signaling pathway and inhibiting inflammation by down-regulation of TNF-α and IL-6." (PMID 30298000, 2018). "The study aims to evaluate the associations between proinflammatory markers (IL-1β, IL-6, and TNF-α) with BTMs in postmenopausal Saudi women with and without osteoporosis." (PMID 28121926, 2017). "The pathogenesis of osteoporosis in chronic inflammatory disease may be secondary to releases of cytokines such as TNF- and IL6." (PMID 26221501, 2015). "IL-1β, IL-6, TNF-α, and the osteoporosis-related protein system OPG/RANK/RANKL may have some synergetic effects on emphysema and bone loss in COPD." (PMID 22176920, 2011). "Experimental studies indicate that IL-1β, IL-6 and TNF-α may play important roles in the etiology of both osteoporosis and emphysema." (PMID 22176920, 2011). "In the absence of estrogen, IL-6 appears to be an upregulator of bone catabolism, leading to osteoporosis or fracture or both, although the relevance of this to hip OA is not known." (PMID 20482813, 2010). "Patients with PBC exhibit elevated levels of inflammatory cytokines, including IL-1, IL-6, TNF-α, which can directly or indirectly promote osteoclast formation and activation via the RANKL-RANK signaling pathway, leading to increased bone resorption and osteoporosis." (PMID 38162659, 2023). "Moreover, the decrease in proinflammatory cytokines including TNF-α, IL-6, and G-CSF might be responsible for the protective effect of GNS on osteoporosis." (PMID 37041523, 2023). "Skeletal muscle secretes various myokines (e.g., myostatin, IL6, IGF-1, irisin) in an autocrine, paracrine, or endocrine manner to regulate the metabolic activities of bone cells in various ways and ultimately contribute to the pathogenesis of osteoporosis mechanisms." (PMID 36578964, 2022). "It was also previously suggested that F. deltoidea extract has potent inflammation inhibitory properties that significantly downregulate the expression of bone inflammatory cytokines such as NF-κβ, TNF-α, and IL-6 to normal levels, as opposed to their excessive increase in osteoporosis." (PMID 33456747, 2020). "When studying NR_024031, also named DANCR, researchers found that DANCR promoted the expression of IL-6 and TNF-α, and DANCR-induced IL-6 and TNF-α had bone-resorbing activity indicating that DANCR is involved in the pathology of osteoporosis and may be a biomarker for postmenopausal osteoporosis." (PMID 28173844, 2017). "By contrast, the bone mineral density of the whole body was correlated with RANKL-induced osteoclasts, but not with TNF- or IL-6-induced osteoclasts, indicating that “inflammatory cytokine-generated osteoclasts” may contribute to the pathology of RA but not to whole-body osteoporosis." (PMID 36172385, 2022).
osteoporosis (continued). "In this study, no causal effect was observed of IL-6 and TNF-β on four measures of PUFAs and five measures of osteoporosis, suggesting that the causal effect of four measures of PUFAs on BMD was not affected by IL-6 and TNF-β, moreover IL-6 and TNF-β could not affect BMD by affecting PUFAs." (PMID 36570136, 2022). "A study involving 45 postmenopausal women showed that the circulating levels of IL-1β, IL-6, and TNF-α in postmenopausal women with osteoporosis were significantly higher than those without osteoporosis." (PMID 37035758, 2023). "The sample sizes for four gene loci, namely, COL1A1 1245GT (rs1800012), IGF1 (rs5742612), IL6 G174C (rs1800795), and ESR1 XbaI (rs9340799), were sufficient for a conclusion of noncorrelation with osteoporosis." (PMID 35452412, 2022). "The aim of the study is to evaluate the association between proinflammatory markers (interleukin [IL]-1β, IL-6, TNF-α) with bone turnover markers (BTMs) in postmenopausal Saudi women with and without osteoporosis." (PMID 28121926, 2017).
Alzheimer disease (308 papers, 2007 to 2026). A progressive, neurodegenerative disease characterized by loss of function and death of nerve cells in several areas of the brain leading to loss of cognitive function such as memory and language. "Pro-inflammatory cytokines such as IL-1, TNF-α, and IL-6 have been linked to neuroinflammation in the CNS and peripheral nervous diseases including MS, Parkinson’s disease (PD), Alzheimer’s disease (AD) and diabetic neuropathy." (PMID 41169367, 2025). "Previous studies have shown that sleep deprivation raises neuroinflammatory biomarkers such as TNF, IL-6, and β-amyloid protein, which is linked to Alzheimer's disease." (PMID 40390711, 2025). "Serum IL-6 levels also increase with age and have been associated with frailty and mortality as well as age-related neurodegenerative diseases such as Alzheimer’s disease." (PMID 40493408, 2025). "Elevations in proinflammatory cytokine levels (e.g., IL-1β, IL-6, and TNFα) are implicated in the development of Alzheimer's Disease [AD]." (PMID 39055623, 2024). "In this research, four inflammatory biomarkers associated with Alzheimer’s disease were found, and among them was IL-6." (PMID 37489445, 2023). "For IL-6, similar results were noted in cohorts of patients with ischemic risk and Alzheimer's disease." (PMID 37560452, 2023). "Further, degenerative CNS diseases such as Alzheimer’s disease as well as MM occur with increased frequency with advancing age and are associated with increased levels of IL-6, which is a potent mediator of inflammation in both diseases." (PMID 36499093, 2022). "The IL-6 trans-signaling pathway is implicated in the pathogenesis of various neuropsychiatric conditions, including Alzheimer’s disease, Parkinson’s disease, and acute UTI-induced delirium-like states." (PMID 36100846, 2022). "Studies found that the elevation of peripheral IL-6 was associated with increased risk of developing Alzheimer’s disease." (PMID 36292623, 2022). "Amyloid beta oligomers are hallmark biomarkers in the etiology of Alzheimer’s disease and induce inflammation characterized by interleukin-6 increase and GFAP upregulation." (PMID 31847143, 2019). "Although mostly studied for its involvement in Alzheimer’s disease, SorLA has recently been shown to be implicated in immune response by regulating IL-6-mediated signaling, as well as driving monocyte migration." (PMID 30666202, 2018). "Previous studies have shown that higher peripheral levels of interleukin-6 (IL-6) are associated with cognitive decline in healthy subjects and in those with Alzheimer’s disease." (PMID 31162410, 2017). "Specifically, cognitive dysfunction, especially Alzheimer's disease (AD), is associated with elevated blood levels of pro-inflammatory markers, such as C-reactive protein and interleukin-6." (PMID 28507516, 2017). "Pro-inflammatory cytokines TNFα and IL-6 are key mediators of inflammatory responses associated with various neurological disorders including Parkinson’s disease, Alzheimer’s disease, and amyotrophic lateral sclerosis." (PMID 29228978, 2017). "We recently showed that IL-1b and IL-6 DNA methylation is modulated in the brain of Alzheimer’s disease patients, and that IL-1b expression is associated to DNA methylation in the brain of patients with tuberous sclerosis complex." (PMID 28954414, 2017). "Dysregulation of IL-6 has been implicated in the modulation of various cognitive functions and previous meta-analyses have reported associations between upregulated peripheral IL-6 with Alzheimer's disease (AD) and postoperative cognitive dysfunction." (PMID 29358917, 2017). "Associations between interleukin 6 (IL-6) polymorphisms and Alzheimer’s disease (AD) remain controversial and ambiguous." (PMID 22701584, 2012). "One of these excessive proinflammatory cytokines, IL-6, is implicated in improper beta-amyloid processing during Alzheimer's disease (AD) due to its effects on alpha-2-macroglobulin (A2M)." (PMID 18171484, 2008).